CXCL2 (C-X-C motif chemokine ligand 2)
Diseases named in the same sentence as CXCL2 in open-access papers (continued):
Sharing a sentence is not in itself a finding about the gene and the disease.
infection (continued). "CXCL2 and CXCL8 recruit PMNs to the site of infection while CCL5 attracts blood monocytes, memory T helper cells and eosinophils." (PMID 26830914, 2016). "In this study, IL-17 administration exacerbates neutrophil infiltration through the induction of CXCL1, CXCL2 and CXCL5 following S. aureus intramammary infection, whereas neutralization of the IL-17 by anti-IL-17 antibody reduced neutrophil infiltration." (PMID 26230498, 2015). "To further explore the role of IL-17 in host defense against S. aureus intramammary infection, we focused on neutrophil-recruiting chemokines that are the key target genes of IL-17, such as CXCL1, CXCL2 and CXCL5." (PMID 26230498, 2015). "To validate transcriptional changes in iHOs after infection with S. Typhimurium SL1344, we carried out further microinjections with PBS or SL1344 and measured the mRNAs for IL-8, IL1B, IL23A, TNF, and CXCL2 with quantitative assays." (PMID 25964470, 2015). "Circulating neutrophils migrate to the infection site along a chemotactic gradient of potent chemoattractants, such as KC (CXCL1 or IL-8 in humans) and MIP-2 (CXCL2), produced at the infection site." (PMID 25974210, 2015). "PMN recruitment to the sites of infection occurs in response to chemotactic stimuli, with CXCL1 and CXCL2 being among the most potent chemokines promoting PMN migration." (PMID 24651866, 2014). "The results showed that PAMs infected with M. hyopneumoniae exhibited significantly increased expression of CCL4, CXCL2 and CXCL10 mRNA at 6 h post-infection, and decreased at a steady-state level, with maximal production at 6 h post-infection." (PMID 25098731, 2014). "LysM-Myd88−/− mice showed a strongly impaired neutrophil influx into the bronchoalveolar space 6 hours after infection with Klebsiella, together with markedly reduced local concentrations of neutrophil attracting mediators such as TNF-α, CXCL1 and CXCL2." (PMID 25254554, 2014). "Corneas from each group were dissected at the indicated time after infection and the expression of TLR4 and CXCL2 were analyzed by RT-PCR." (PMID 24633052, 2014). "In B6 mice, three genes, Cxcl2 and the IFN-inducible gene Oasl2 (in myeloid cells) and Cxcl1 (in fibroblasts), tended to peak in expression at Day 7 post-infection." (PMID 24967703, 2014). "Addition of Bb induced up-regulation of transcript levels for all chemokines assessed, including CXCL1, CXCL2, CCL2, CCL3, CCL4, and CCL5 by MØs and DCs as early as 4h post-infection." (PMID 24367705, 2013). "MIP-2 (CXCL2) and KC (CXCL1) belong to the CXC chemokines, which are potent chemoattractants involved in neutrophil recruitment to the site of infection." (PMID 24039581, 2013). "In contrast, the chemokines CXCL1 and CXCL2, by binding to CXCR2, promote rapid release of neutrophils from the bone marrow, thereby elevating blood neutrophil counts during infection or during G-CSF-induced neutrophil mobilization." (PMID 21738479, 2011). "On day 7 post-infection, protein levels of IFN-γ, TNF-α, and CXCL2 in the adult lung increased with higher doses of SeV." (PMID 22185352, 2011). "Twenty-four h after RV1B infection, CXCL1/KC, CXCL2/MIP-2, IL-6, CCL2/MCP-1 and IFN-γ expression in wild-type mice increased 3–5 fold." (PMID 21637773, 2011). "Additionally, chemokine-encoding genes involved in the recruitment of immune cells such as CXCL2, CXCL3 and CCL20 were upregulated during the course of infection." (PMID 40794782, 2025). "In the case of MHV-JHM infection, changes in expression (from 0% to 100%) were visible in IL-6, IL-18, IL-33, ENA-78 (CXCL5), GRO alpha (CXCL1), IP-10 (CXCL10), MCP-1 (CCL2), MIP-1 beta (CCL4), MIP-2 alpha (CXCL2), RANTES (CCL5), and TNF alpha." (PMID 40358160, 2025). "CXCL1, CXCL2 and CXCL8 produce a local inflammatory response when infection or injury occurs." (PMID 39656442, 2024).
infection (continued). "When macrophages detect microbial products, they initiate the inflammation program, producing chemokines and cytokines (such as IFNS, CXCL1, CCL2, TNFA, CXCl2, IL1B) necessary for recruiting leucocytes and upregulating neutrophil-killing capacity to resolve the infection." (PMID 39298265, 2024). "Matching the data collected during the physical characterization of the NTHi-NHNE infection, expression levels of key chemo- and cytokines (e.g. CXCL8, IL-6, IL-1β, CCL3, CXCL1 & CXCL2) and genes involved in ECM remodelling and inflammation (PLAU, Serpine1, MMP9) increased further on day14." (PMID 38990812, 2024). "Also, in immunized horses with an attenuated vaccine, the transcriptome analysis of immune responses in PBMCs after in vitro infection with AHSV revealed the up-regulation of genes of different cytokines such as IL-6, TNF, CXCL2 and IL-1β." (PMID 38396742, 2024). "Therefore, to assess the role of CXCL1, CXCL2, CXCL3, and CXCL5 in neutrophil trafficking during infection with C. violaceum, we used a CXCR2 inhibitor." (PMID 38352492, 2024). "Histological findings of immune cell infiltration in tracheal tissues after infection with swH1N1 was in line with induction of cytokines and chemotactic factors (AMCF-II, CXCL8/IL8, CXCL2, CXCL10, and CCL20) as well as receptors (CCR1 and CXCR2) in lower trachea after this infection." (PMID 39247193, 2024). "Compared to sham-infected and placebo-treated groups, RV-A1-infected and ECSN6-treated animals showed increase in Cxcl2 and Cxcl10 at 24 h post infection but not Tnf-α and Muc5ac." (PMID 39538325, 2024). "Although CXCL2 is also a CXCR2 ligand and plays an important role in neutrophil recruitment to sites of infection, CXCL2 levels did not change in the blood or alveoli of both infected or uninfected groups." (PMID 37275853, 2023). "At 18 hr post-infection, even though there was a higher amount of neutrophils in the airways of Ptx3−/− mice, we did not detect any differences in the levels of CXCL1 and CXCL2 between Ptx3-deficient and WT mice." (PMID 37222419, 2023). "However, CLEC2.Fc efficiently inhibited the expression of proinflammatory cytokines (IL‐6, TNF‐α, IFN‐γ, and IL‐10) and chemokines (CXCL1, CXCL2, CXCL5, CCL2, IP‐10) at day 3 and day 5 post‐infection (blue columns)." (PMID 37211986, 2023). "Upon infection, chemoattractants such as CXCL1, CXCL2 and IL-17 are produced in the lung, leading to further neutrophil recruitment and transmigration into the tissue, a process that is highly dependent on C-C chemokine receptor type 2 (CCR2)-positive blood monocytes." (PMID 37566060, 2023). "Our previous study found that infection with meningitic E. coli can significantly increase the expression of chemokines and cytokines, such as IL-6, IL-1β, TNF-α, CXCL3, CXCL2, and C-C motif chemokine ligand (CCL) 2, and some chemokines remain at high levels in the blood and brain for a long time." (PMID 37445610, 2023). "Furthermore, upon infection with Shiga-toxin-producing enterohemorrhagic E. coli, neutrophil recruitment was dependent on TNF-α, CXCL1 and CXCL2 produced by tissue-resident macrophages and was directly associated with kidney injury and poor disease outcomes." (PMID 37566060, 2023). "Notably, ILC3 production of LT has been described in the intestine during Citrobacter rodentium infection, and LTβR signaling in intestinal epithelial cells was required for recruitment of neutrophils to the infection site via production of CXCL1 and CXCL2." (PMID 35845169, 2022). "CXCL2 belongs to the CXC chemokine family and is synthesized by a variety of cell types, such as monocytes, macrophages, and epithelial cells in response to infection or injury." (PMID 34024010, 2022). "In addition to CXCL8, SpyCEP cleaves all neutrophil-specific chemokines that possess an ELR motif, namely, CXCL1, CXCL2, CXCL3, CXCL5, CXCL6, and CXCL7, thereby inhibiting the recruitment of neutrophils to sites of infection and inflammation." (PMID 34649250, 2022).
infection (continued). "IL-1β, TNF-α, CXCL1, and CXCL2 were significantly decreased in fibrotic mice compared with nonfibrotic mice after infection, both at the protein and mRNA levels." (PMID 34990413, 2022). "The chemokine CXCL2 is critical for macrophage, monocyte, and neutrophil migration and is also known to facilitate the clearance of SARS-CoV2 in the absence of CD4 + and CD8 + T cells or neutralizing antibodies beyond 12 days of infection." (PMID 36510222, 2022). "In our infection model, up-regulated Tlr-4 might have activated these pathways to eventually lead to the expressions of proinflammatory cytokiness such as CXCL1, CXCL2, etc." (PMID 36140754, 2022). "In addition, inflammation-related genes including NLRP3, IFI16, IL6, IL1A, CXCL2, and CCL6 were upregulated, further confirming that infection by T. gondii induces a robust immune response to limit infection." (PMID 35012632, 2022). "Activation of these transcription factors may lead to expression of various cytokines genes such as IL1B, CXCL2 and CXCL3, which in turn recruits immune cells to the site of infection." (PMID 37193047, 2022). "The concentration of certain cytokines, including CCL11, IL-1β, IL-5 and CXCL2 were similar between infected and control mice throughout the course of infection (not shown)." (PMID 35812400, 2022). "The infection of epithelial cells has been reported to lead to the production of several cytokines, including interferons (IFNs), interleukins (IL) IL-18, IL-1, and chemokines such as KC (CXCL1) and MIP-2 (CXCL2)." (PMID 34012447, 2021). "Furthermore, expression of chemokine genes Ccl3, Cxcl2 and Cxcl10 also significantly increased in migratory ILCs after STM infection." (PMID 33414524, 2021). "Cxcl1 and Cxcl2 regulated by Mir22 and Mir155 are chemokines which signal through CXC receptor 2 to attract neutrophils to the place of inflammation, which is essential to control tissue infection." (PMID 34527215, 2021). "Furthermore, CXCL2, CXCL,3, and CCL20 were found upregulated and identified in early infection models of SARS-CoV-2." (PMID 33602138, 2021). "TNF (degree = 11), CXCL2 (degree = 8), CSF3 (degree = 5), HIST2H2BE (degree = 11) and FGF2 (degree = 10) family proteins were activated and had a strong interaction, indicating that cells had a strong inflammatory response after infection." (PMID 34632719, 2021). "In addition, CXCL1, CXCL2, and CXCL5 suppress excess CXCL13 expression in macrophages via the CXCR2 axis during the early infection stage." (PMID 34868067, 2021). "After infection, the 1A3, 6A2 variants, and KO male mice, and female 1A0 and 6A4 variants (but not males) exhibited higher expression levels of CXCL2 in response to infection." (PMID 32670284, 2020). "Furthermore, we verified the upregulation of CXCL8, CXCL2, CXCL3, IFNλ-1, -2 and IFIT-2 genes following an apical infection of HIBCPP cells with E-30 at MOI 20 compared to uninfected condition." (PMID 32872518, 2020). "Furthermore, upon infection the bronchoalveolar and thoracic cavity lavage of S100A8/A9-/- mice showed increased concentrations of CXCL-1, CXCL-2, CXCL-5, as well as elastase in comparison to the WT controls." (PMID 32107497, 2020). "Pre-infection blockade of TNFR1 was found to significantly reduce neutrophil number and activation status, consistent with the concomitant reduction of pro-neutrophilic chemokine Cxcl1 and Cxcl2." (PMID 33080861, 2020). "Neutrophils are recruited to the infection site by chemokines such as CXCL1 and CXCL2." (PMID 32093731, 2020). "IL-1β, CXCL1, CXCL2, and CCL2 expression was significantly higher in the lungs of klotho KO mice infected with A. baumannii than in those of klotho WT mice at 1 day post-infection." (PMID 33329595, 2020). "Similarly, we performed qRT-PCR analysis of proinflammatory cytokines (Tnf, Il6, and Cxcl2) in both SIRT3 WT and SIRT3 KO BMDMs or PMs, which were pretreated with 3-TYP prior to Mabc-R infection." (PMID 32835604, 2020).
infection (continued). "Among them, Cxcl1, Cxcl2, Cxcl3, Cxcl10, IL1b, Socs3, and Mmp14 were overexpressed more than 100-fold compared with the non-infected sample regardless of infection type." (PMID 30858471, 2019). "Melatonin treatment (30 nM) reduced the levels of IL-6 (2-fold), MCP-1/CCL2 (5-fold), and RANTES/CCL5 (6-fold) compared to vehicle treatment after both 4 and 24 h of infection, while both vehicle and melatonin treatment reduced the levels of IL-10, MIP-2/CXCL2, and KC/CXCL1." (PMID 30949455, 2019). "In the lungs, the levels of proinflammatory cytokines, including interleukin-1β (IL-1β) and granulocyte colony-stimulating factor (G-CSF), and of chemokines, including IP10/CXCL10, MIP1-α/CCL3, MIP1-β/CCL4, MIP2/CXCL2, and KC/CXCL1, were increased and remained high after the infection with WT cells." (PMID 30940711, 2019). "Growth factors and chemokines that support myeloid cell influx and expansion after infection, including M-CSF, G-CSF, MCP-1 (CCL2), MIP-1α (CCL3), MIP-1β (CCL4), KC (CXCL1) and MIP-2 (CXCL2), are also highly abundant in S. aureus infected femurs relative to mock infected femurs." (PMID 30978245, 2019). "Therefore, using qPCR, we determined the expression of a variety of cytokines with neutrophil chemotactic properties including IL-6, CCL3, CXCL2 and G-CSF, as well as pro-inflammatory cytokines IL-1β and TNF-α at day 3 (105 PFUs) post-infection." (PMID 30787331, 2019). "Further guidance to sites of infection is provided by a family of CXCL8 chemokines originating from concentrated sites of PAMPs and DAMPs, including CXCL1, CXCL2, CXCL3, CXCL5, CXCL6, CXCL7, and CXCL8 (IL-8), which are sensed by CXCR1 and CXCR2 on neutrophils and monocytes." (PMID 30791481, 2019). "CXCL2 is highly homologous and shares many of the same roles in acute inflammation as CXCL1, including interaction with the CXCR2 receptor, secretion by monocytes and macrophages, and attraction of neutrophils to sites of infection and inflammation." (PMID 29661181, 2018). "For example, LTβR−/− mice are sensitive to bacterial infection due to the absence of lymphoid organs in these mice, and LTβR signaling in intestinal epithelial cells is required for the recruitment of neutrophils to the site of infection during early infection via the production of CXCL1 and CXCL2." (PMID 30469426, 2018). "This pattern did not apply to Lcn2−/− mice, where the Cxcl2 mRNA levels are unaltered indicating lack of infection control at week 5 compared to WT." (PMID 30534124, 2018). "We report a strong induction of numerous pro-inflammatory cytokines, chemokines and AMPs such as CXCL1, CXCL2, CXCL5, CXCL8, CCL20, TNFα, TSLP, IL-23α, IL-32, IL-6, hBD2 and S100A7 during the infection of monolayered primary keratinocytes and reconstructed epidermis with the wild-type PAK strain." (PMID 30070169, 2018). "Consistent with greater neutrophil numbers, mice infected with virus expressing NS1-wt exhibited 7.5-fold and 15-fold greater CXCL1 and CXCL2 gene expression, respectively, in their lungs compared with mice infected with virus expressing NS1-Y84F on day 1 post-infection." (PMID 28498306, 2017). "Meanwhile, the chemokine levels were similar to the proinflammatory cytokine levels in BALF; geldanamycin-treated mice produced significantly less MIP-1α, MCP-1, CXCL-2, IP-10, and RANTES on days 2, 4, and 7 after infection than the vehicle-treated mice and oseltamivir-treated mice." (PMID 28664154, 2017). "Interestingly, IFNβ, CXCL2 and TNF expression control by the M protein is observed in the late stages of the infection in vivo, further corroborating the modulation by MTha of the immune response observed in cellulo." (PMID 29084252, 2017). "Following infection, expression levels of the immunomodulatory cytokines C-C motif chemokine 22 (CCL22), CCL1, IL-23α, IL-3, IL-4, matrix metalloproteinase 9 (MMP9), IL-21, C-X-C motif chemokine 2 (CXCL2), and CCL2 were increased." (PMID 28507072, 2017).
infection (continued). "As one of the most crucial proinflammatory cytokines, IL-17A plays an important role in host defense against pathogen infection by stimulating cytokines (TNF-α, GM-CSF, etc) and chemokines (CXCL1, CXCL2, IL-8, etc) expression leading to neutrophil expansion and chemotaxis." (PMID 28035060, 2017). "After 9 days of infection, neither Tha nor Th4M induce the expression of IFNß, CXCL2 or TNF in BALB/c." (PMID 29084252, 2017). "CXCL-2 and CXCL1 are chemoattractive for neutrophils as they recruit them to the site of infection." (PMID 26974438, 2016). "Ccl3 is elevated in response to ANDV infection, but not SNV infection, whereas Cxcl2 levels are similarly elevated with MAPV and SNV infection, but much higher in ANDV infection." (PMID 27763552, 2016). "Therefore the increase of transcription of CXCL2, IL8 and TNF observed in the case of Th4M infection appeared to be dependent of RelAp43 and of the 4 positions mutated in Th4M." (PMID 28000711, 2016). "Using cells only treated with IL-33 or cells only infected with HTNV as controls, the mRNA expression of IL-1β, IL-6, IL-8, CCL2, CCL20, CXCL1, CXCL2, and CX3CL1 was significantly induced in HUVECs prior to infection with HTNV (MOI = 1) for 48 h and then exposed to IL-33 (20 ng/ml) for 6 h." (PMID 25658420, 2015). "Besides CXC chemokines, CXCL1 and CXCL2, the activated components of a complement cascade, e.g. C3a and C5a, were shown to be potent chemoattractants for PMN localization to the sites of infection." (PMID 24651866, 2014). "These reductions were observed as early as 1 day after the infection and appears to be long-lasting, being still present at 3 days post-infection, a time at which BAL neutrophilia, lung neutrophilic infiltration and Mpo and CxCl2 expression were drastically reduced." (PMID 25375146, 2014). "A significant time-dependent increase in Cxcl2 and Cxcl5 mRNA expression was measured after infection by WT or the complemented ΔinvC pinvC but not SPI1-deficient non-invasive Salmonella." (PMID 25210785, 2014). "Infection with both low and high virulence isolates resulted in down-regulation of mRNA levels for chemokines CCL2, CCL3L, CXCL2 and chemokine receptors CCR1, CCR5, CXCR3, CXCR4 and up-regulation in expression of mRNAs for CCL4, CXCL10 and chemokine receptor CCR7." (PMID 23265239, 2013). "By contrast, at 7 days post infection, the levels of CCL2, CCL3, CXCL2, IFN-γ and the anti-inflammatory cytokine IL-10 were significantly lower in influenza A virus-infected Nox1−/y lung compared to WT control, whereas IL-β, IL-6, TNF-α, and GM-CSF were similar between the two strains of mice." (PMID 23577160, 2013). "Also contrasting with the results described here from the studies of in vivo infections, levels of mRNA for CCL3, CXCL2, CCR1 and CCR5 were down-regulated compared to mock-infected cells following infection in vitro." (PMID 24083897, 2013). "Indeed, transcription of CXCL1 (up to 3 fold increase), CXCL2 (up to 3.9 fold) and CXCL3 (up to 2 fold) (alias respectively GROα, GROβ, GROγ) was rapidly induced and persisted during the first 12 hours of infection." (PMID 22928052, 2012). "The expression of 277 genes was induced >2-fold in a statistically significant manner by infection with Mtb:Δ-sigH at the 0 hr time-point Some of the genes with the greatest induction included CCL4 (17.6-fold), CXCL2 (10-fold), CCL7 (6.5-fold) and CCL20 (4.3-fold)." (PMID 22235255, 2012). "CXCL2, CCL2 and IFN-λ levels were also decreased to varying degrees one day after infection." (PMID 21637773, 2011). "Following experimental infection with the neurotropic viruses including the JHM strain of mouse hepatitis virus (JHMV) or Theiler's murine encephalomyelitis virus (TMEV), both CXCL1 and CXCL2 are up regulated within the CNS." (PMID 20596532, 2010). "Thus, Listeria-infection induces significant epithelial ROI synthesis, which in turn mediates MAP kinase Erk activation and downstream Cxcl-2 production." (PMID 21124989, 2010).